FADD (Fas associated via death domain)
Diseases named in the same sentence as FADD in open-access papers (continued):
Sharing a sentence is not in itself a finding about the gene and the disease.
breast tumors (3 papers, 2003 to 2015). "IHC staining was assessable in 258 of the 500 primary breast tumors for cortactin and in 295 for FADD." (PMID 18823530, 2008). "However, there were no detectable differences in the expression levels of caspase-8 and FADD between SK-BR-3 and MDA-MB-231 breast tumour cells showing different sensitivities to TRAIL." (PMID 12644829, 2003).
Hyperglycemia (3 papers, 2020 to 2024). An increased concentration of glucose in the blood. "Uncontrolled hyperglycemia can then exacerbate β-cell ER stress, under which condition THADA aggravates ER stress-induced apoptosis through the pro-apoptotic complex of DR5/FADD/caspase-8." (PMID 36823211, 2023).
ischemic stroke (3 papers, 2022 to 2023). A stroke disorder caused by obstruction of blood flow to the brain, due to thrombotic (local blood clot formation) or embolic (due to a blood clot or other material traveling from another site) event. "Elevated levels of FADD (Fas-associated protein with death domain) and caspase-8 were associated with an increased incidence of ischemic stroke." (PMID 37305740, 2023). "Cohort studies reported that a high plasma level of FADD was associated with increased incidence of coronary events and ischemic stroke." (PMID 35213968, 2022). "In addition, the incidence of ischemic stroke is highly associated with the expression of Fas, Fas-associated death domain protein (FADD) and caspase-8." (PMID 36824441, 2022).
myocardial infarction (3 papers, 2017 to 2023). Gross necrosis of the myocardium, as a result of interruption of the blood supply to the area, as in coronary thrombosis. "Apart from cancer, the top-ranked lncRNA H19 associated with myocardial infarction has been reported to bind directly to miR-103/107 and regulate FADD expression and necrosis." (PMID 28051121, 2017). "FADD upregulation promoted necrosis and improved myocardial infarction by influencing the formation of RIPK1 and RIPK3 complexes." (PMID 36348274, 2022).
neuroblastoma (3 papers, 2021 to 2023). Neuroblastoma (NB) is the most common solid, extracranial childhood tumor. "Notably, the authors have determined that Aβ1–42 induces p-PKR phosphorylation, increases FADD levels, and promotes physical interaction between PKR and FADD in the nucleus of neuroblastoma cells." (PMID 33994991, 2021). "In neuroblastoma, studies have shown that genistein downregulates survival proteins (e.g., BCL2) and induces death factors and death domains (e.g., TNFR-1, TRADD, FADD)." (PMID 38249515, 2023).
Obesity (3 papers, 2016 to 2024). Accumulation of substantial excess body fat. "As a result, FADD‐D mutation or adipose‐specific FADD disruption in mice prevents obesity induced by leptin deficiency or by a HFD feeding." (PMID 27357657, 2016). "It is possible that FAS and FADD work together to play a critical role in obesity and obesity‐associated pathologies." (PMID 27357657, 2016). "As a result, FADD‐D mutation or adipose‐specific FADD disruption in mice prevents obesity induced by leptin deficiency or by feeding on a HFD." (PMID 27357657, 2016). "Overall, FADD deletion‐associated reprogramming of glucose and lipid metabolism might contribute to obesity resistance." (PMID 27357657, 2016). "GTTs and ITTs were performed to investigate the role of adipocyte‐specific FADD deletion in insulin resistance induced by obesity." (PMID 27357657, 2016). "Using the adipose‐specific aP2‐Cre transgene, adipose‐specific deletion (ad‐FADD) mice were created via the Cre/LoxP system to further study the specific role of FADD in insulin resistance and obesity." (PMID 27357657, 2016). "Similar metabolic phenotypes, such as reduced fat formation, insulin resistance, and resistance to HFD‐induced obesity, are shown in adipose‐specific FADD knockout mice." (PMID 27357657, 2016). "Consistently, we demonstrated that FADD deletion in adipocyte alleviated diet‐induced obesity and glucose intolerance in mice." (PMID 27357657, 2016). "We conclude that FADD is a master regulator of glucose and fat metabolism with potential applications for treatment of insulin resistance and obesity." (PMID 27357657, 2016). "We further generated and characterized mice mutant in both leptin and FADD by introducing the FADD‐D allele into the leptin‐deficient (ob/ob) mice to investigate the genetic influence of FADD in obesity." (PMID 27357657, 2016). "Therefore, targeted inhibition of FADD in adipocytes emerges as a promising strategy for combating obesity and insulin resistance." (PMID 39009585, 2024). "Ad‐FADD mice exhibited similar metabolic phenotypes with FADD‐D mice, including reduced fat formation, decreased adipose tissue inflammation, insulin resistance, and resistance to high‐fat diet (HFD)‐caused obesity." (PMID 27357657, 2016). "We present here that FADD, a classic apoptotic adaptor protein in death receptor signaling, is a master regulator of fat and glucose metabolism with potential applications for treatment of obesity and insulin resistance." (PMID 27357657, 2016). "In addition, mice, after 15 weeks of high-energy feeding, were found with down-regulated FADD and were not as obese as wild-type mice, which confirmed that the body may affect metabolism through down-regulation of FADD and decrease the impact of obesity." (PMID 36439361, 2022). "Therefore, compounds inhibiting FADD activity in adipose tissue might have therapeutic potential for preventing insulin resistance and obesity." (PMID 27357657, 2016).
oral cancer (3 papers, 2018 to 2023). "In oral carcinoma located in the tongue, the expression of FADD (Fas-associated death domain-containing protein) was higher than that in adjacent areas." (PMID 30417146, 2018). "Moreover, constitutively phosphoryl-mimicking mutation of FADD also enhances Notch-1 signaling in muscle regeneration through promoting ERK phosphorylation is consistent with our finding in oral cancer cells." (PMID 35249111, 2022). "FADD amplification was found to correlate with gender distinction, possibly accounting for the observed twofold increased frequency of oral cancer occurrence in males compared with females." (PMID 30417146, 2018).
rheumatoid arthritis (3 papers, 2019 to 2024). A chronic, systemic autoimmune disorder characterized by inflammation in the synovial membranes and articular surfaces. "Interestingly, the regulatory connection of FADD was demonstrated with rheumatoid arthritis, and it has been suggested that FADD negatively regulates IL-1R/TLR4 signaling." (PMID 38542202, 2024). "Moreover, our results establish human soluble FADD as a marker of joint inflammation during rheumatoid arthritis (RA) and gout attack, two inflammatory rheumatic diseases involving the NLRP3 inflammasome." (PMID 30804327, 2019). "Finally, we established human soluble FADD as a new marker of joint inflammation in gout and rheumatoid arthritis, two rheumatic diseases involving the NLRP3 inflammasome." (PMID 30804327, 2019). "Compared to the control group, the synovial membrane of the rheumatoid arthritis (RA) model group showed a significantly reduced abundance of FADD positive vehicles compared to the control group." (PMID 38919260, 2024). "This study delved into the intricate landscape of rheumatoid arthritis and provided exclusive insights into the role of miRNA128a, the TLR4 signaling pathway and adenosine in RA pathogenesis by modulating FADD tissue expression and FADD microvesicular shedding in synovial fluid." (PMID 38919260, 2024). "FADD has the potential to be exploited for the treatment of non-cancer diseases, such as rheumatoid arthritis (RA)." (PMID 38542202, 2024). "Unlike the cohort with rheumatoid arthritis, the cohorts receiving TMZ, MTX and the combination thereof exhibited a substantially higher prevalence of FADD positive vesicles." (PMID 38919260, 2024).
Sepsis (3 papers, 2017 to 2025). Sepsis is defined as life-threatening organ dysfunction caused by a dysregulated host response to infection. "Additional studies have demonstrated that inhibition of apoptosis following CLP-induced sepsis through treatment with siRNA against caspases or FAS-associated death domain (FADD) rescues septic EC dysfunction, including reducing septic hyperpermeability." (PMID 28250575, 2017). "The protein expression levels of four upregulated necroptosis‐related DEGs (PYGL, TNF‐α, CYLD and FADD) were significantly higher in the sepsis group than in the control group in all three cells, whereas the TLR3 level was only significantly higher in HUVEC cells." (PMID 40318009, 2025).
T-cell leukemia (3 papers, 2009 to 2024). A malignant disease of the T-lymphocytes in the bone marrow, thymus, and/or blood. "The pivotal role of miR-128a in modulating Fas-mediated apoptosis in human T-cell leukemia by directly targeting FADD led us to further explore their interplay in the realm of RA." (PMID 38919260, 2024). "In T cell leukemia cells resistant to Fas-induced apoptosis, the demethylation process leads to an increase in miR-128a levels that bind directly to the 3-UTR of FADD, causing delayed onset of apoptosis." (PMID 38919260, 2024). "Previous evidence has indicated that miR-128a plays a crucial role in modulating Fas-mediated apoptosis in human T cell leukemia by directly targeting FADD, suggesting that mi-RNA128a could be an epigenetic regulator of the FADD protein in RA." (PMID 38919260, 2024). "First, conventional anti-cancer drugs induce primarily apoptosis in T-cell leukemia Jurkat cells and the knockout of the FADD or the combined knockout of all executioner caspase genes (i.e., caspase 3, 6, and 7) disables cell death upon common anti-cancer drugs treatments." (PMID 33800107, 2021).
acute leukemia (2 papers, 2010 to 2017). A clonal (malignant) hematopoietic disorder with an acute onset, affecting the bone marrow and the peripheral blood. "Here, we report that Sorafenib inhibits necroptotic signaling and cell death in acute leukemia cells, when caspase activation and apoptosis are blocked by FADD deficiency or zVAD.fmk." (PMID 28978109, 2017). "In the present study, we show that apoptosis induction and histone alterations by PCI-24781, a novel hydroxamic acid-based HDAC inhibitor, require caspase-8 and the adaptor molecule, Fas-associated death domain (FADD), in acute leukemia cells." (PMID 20145726, 2010). "Our current study seeks to extend these mechanistic studies to acute leukemia cells and to clarify the specific role of caspase-8 and the adaptor molecule Fas-associated death domain (FADD) in the mechanism of apoptosis induced by PCI-24781." (PMID 20145726, 2010).
Alzheimer disease (2 papers, 2017 to 2025). A progressive, neurodegenerative disease characterized by loss of function and death of nerve cells in several areas of the brain leading to loss of cognitive function such as memory and language. "Previous studies have indicated that FADD gene expression is elevated in Parkinson's and Alzheimer's diseases, and other neurodegenerative disorders." (PMID 41203125, 2025).
autoimmune disease (2 papers, 2012 to 2017). A disorder resulting from loss of function or tissue destruction of an organ or multiple organs, arising from humoral or cellular immune responses of the individual to their own tissue constituents. "However, FADD deletion does not lead to the lpr-like lymphocyte accumulative-autoimmune diseases, as seen in Fas-deficient mice." (PMID 28301594, 2017). "However, despite the essential role of FADD in Fas-induced apoptosis in B cells, mice with B cell specific FADD depletion, even aged, did not exhibit B cell-related autoimmune diseases which are characteristic of Fas deficiency." (PMID 22848207, 2012).
B cell lymphoma (2 papers, 2016 to 2021). "A similar scenario has been previously reported in T-cell tumors and B-cell non-Hodgkin lymphoma, where both phospho-FADD positivity and signal intensity exhibited a high variation." (PMID 27556297, 2016).
breast invasive carcinoma (2 papers, 2022 to 2023). "explored the prognostic value of PPFIA1 alone or in combination with TMEM16A and FADD in patients with invasive breast cancer and found that combined expression was significantly associated with perineural invasion and a low disease-free survival rate." (PMID 37158817, 2023).
COVID-19 (2 papers, 2021 to 2023). A disease caused by infection with severe acute respiratory syndrome coronavirus 2. "Activation of ISGs appear to be beneficial in controlling SARS-CoV-2, but over-activation of proinflammatory cytokines and downregulation of certain ISGs (IFNA1, APOBEC3G, and FADD) and microRNAs (miR-155 and miR-130a) may be associated with progression to severe/critical COVID-19." (PMID 33780352, 2021). "In COVID-19, the necroptosis pathways of MLKL-, fas-associated death domain (FADD)-, and apoptosis-associated speck-like protein containing a caspase recruitment domain (ASC)-related genes are likely to be involved in lymphopenia and might potentially predict the COVID-19 outcome." (PMID 38001795, 2023).
dementia (2 papers, 2013 to 2017). Loss of intellectual abilities interfering with an individual's social and occupational functions. "Overall, the present data suggests FADD as a putative biomarker of the cognitive decline associated with the course of clinical dementia." (PMID 28320441, 2017). "The present data suggests FADD as a putative biomarker for pathological processes associated with the course of clinical dementia." (PMID 28320441, 2017). "Immunofluorescence assays were performed to characterize FADD at the cellular and anatomical levels, and to evaluate possible changes in FADD expression patterns in subjects with clinical dementia as compared to NCI controls." (PMID 28320441, 2017). "Pro-apoptotic FADD was lower in an elderly community-based cohort of subjects with dementia, contrary to the initial prediction of a higher level." (PMID 28320441, 2017). "For example, a MAP participant with average demographic and pathologic characteristics had a 2.5 fold-higher likelihood of dementia if the cortical density of FADD is in the lower quartile versus the higher quartile." (PMID 28320441, 2017). "In contrast, subjects with clinical dementia presented an anomalous FADD distribution, with FADD presence in tangles and in dystrophic neurites, represented by the colocalization observed between FADD and pathological tau (i.e., Alz-50 immunoreacctivity)." (PMID 28320441, 2017). "Perhaps, this type of interaction between FADD and amyloid-β may play a role in the transition from non-dementia (either NCI or MCI) to dementia." (PMID 28320441, 2017). "FADD was reportedly involved in brain dopamine signaling, while SOCS3 can promote progression toward human immunodeficiency virus (HIV)-associated dementia in patients with HIV." (PMID 23936146, 2013). "Interestingly, lower FADD in the DLPFC of MAP subjects was associated with greater amyloid-β cortical accumulation, reduced synaptic density, microglial activation, lower cognitive function, and higher odds of dementia." (PMID 28320441, 2017). "Interestingly, loss of FADD in the DLPFC was associated with a greater load of amyloid pathology, loss of presynaptic terminal markers, poorer cognitive function and increased risk of dementia." (PMID 28320441, 2017). "Therefore, it is reasonable to speculate that FADD might participate in the process of connecting these two classical pathological markers in the progress of clinical dementia, opening room for further studies." (PMID 28320441, 2017). "Cortical FADD immunodensity did not mediate the large effects of the DLPFC tauopathy on cognitive function; and surprisingly had no impact on the risk of clinical dementia in the current MAP sample." (PMID 28320441, 2017). "Interestingly, the effect of DLPFC amyloid-β load on the likelihood of dementia, which was marginally significant when the FADD data was not included in the model (data not shown), was not significant after addition of FADD suggesting a mediation effect." (PMID 28320441, 2017). "Interestingly, this study found marked reductions in FADD (i.e., pro-apoptotic form), but not p-FADD (i.e., anti-apoptotic form), in the DLPFC of MAP participants displaying clinical dementia and/or a large burden of AD pathology." (PMID 28320441, 2017).
fibrosarcoma (2 papers, 2009 to 2023). A malignant mesenchymal fibroblastic neoplasm affecting the soft tissue and bone. "Interaction of FADD and caspase-8 with TNFR signalling proteins is an essential feature in transformed fibrosarcoma cells on TNF stimulation." (PMID 19826422, 2009).
gastric adenocarcinoma (2 papers, 2019 to 2022). "In NSCLC, four missense mutations of FADD were detected in 80 samples (5%), whereas only one FADD mutation was found in 98 colorectal adenocarcinomas (1%) and no FADD mutation was detected in 116 advanced gastric adenocarcinomas." (PMID 31569512, 2019).
heart failure (2 papers, 2013 to 2023). Inability of the heart to pump blood at an adequate rate to meet tissue metabolic requirements. "FADD deletion attenuates cardiomyocyte death and improves cardiac function, ultimately protecting the ischemic heart from heart failure." (PMID 24058479, 2013). "Our data supports the further investigation of FADD as a potential target for genetic manipulation in the treatment of heart failure." (PMID 24058479, 2013). "The aim of the current study was to test whether FADD could be a potential target of gene therapy in the treatment of heart failure." (PMID 24058479, 2013).
Hepatitis (2 papers, 2017 to 2020). Inflammation of the liver. "In NEMO-deficiency-driven HCC, FADD deletion was shown to rescue from aberrant apoptosis, hepatitis, and carcinoma development independently of TRAIL-R." (PMID 28212753, 2017).
hepatoblastoma (2 papers, 2021 to 2024). Hepatoblastoma (HB) is a malignant hepatic tumor and is the most common pediatric liver cancer. "The molecular pathways involved in H19-induced apoptosis in hepatoblastoma cells were discovered, and it was found that H19 suppressed the growth of hepatoblastoma cells by promoting apoptosis via the miR-675/FADD and miR-138/PTK2 signaling pathways." (PMID 38355574, 2024). "In hepatoblastoma, miR-675-mediated downregulation of FADD was found to reduce cell apoptosis and promote tumorigenesis." (PMID 34409922, 2021). "Finally, both the increased expression of PTK2 and reduced expression of FADD lead to the inhibition of cell apoptosis, thus promoting the tumorigenesis of hepatoblastoma." (PMID 38355574, 2024).
Insulin resistance (2 papers, 2016 to 2024). Increased resistance towards insulin, that is, diminished effectiveness of insulin in reducing blood glucose levels. "Taken together, our results suggest that adipocyte‐specific FADD deletion improves HFD‐induced insulin resistance and glucose tolerance." (PMID 27357657, 2016).
ischemia (2 papers, 2013 to 2023). A hypoperfusion of the BLOOD through an organ or tissue caused by a PATHOLOGIC CONSTRICTION or obstruction of its BLOOD VESSELS, or an absence of BLOOD CIRCULATION. "In the present study, we utilized cardiac-specific FADD−/− mice and demonstrated that FADD deletion improved post-ischemic cardiac function and alleviated post-ischemia cardiomyocytes apoptosis." (PMID 24058479, 2013). "Taken together, these data supports the fact that FADD deletion attenuates cardiac death in permanent coronary occlusion (long-term ischemia) model." (PMID 24058479, 2013).
malignant glioma (2 papers, 2013 to 2022). A grade III or grade IV glioma arising from the central nervous system. "The retroviral transfer of FADD gene significantly suppressed survival in malignant glioma cells by induction of apoptosis." (PMID 36348274, 2022).